NBEAL1 (neurobeachin like 1)
Synonyms: ALS2CR16; ALS2CR17; MGC164581; A530083I02Rik
Tractability: PROTAC: ubiquitination databases record sites on it; its protein half-life has been measured.
Gene: Protein-coding gene on chromosome 2 (203,014,608 to 203,226,378, forward strand). Ensembl gene ENSG00000144426.
Subcellular location (Human Protein Atlas): Nucleoplasm; Cytosol
Gene Ontology:
Cellular component: cytosol; membrane
Genetic constraint (gnomAD): Loss-of-function variants: 159 observed, 199.92 expected, observed/expected ratio (o/e) 0.8, 90% interval 0.7 to 0.91. The upper end of that interval is the gene's LOEUF score, 0.91, which puts it in group 3 of 6, group 1 being the genes least tolerant of losing a copy. Missense variants: 1,933 observed, 2,078.5 expected, observed/expected ratio (o/e) 0.93, 90% interval 0.89 to 0.97. Synonymous variants: 699 observed, 713.19 expected, observed/expected ratio (o/e) 0.98, 90% interval 0.92 to 1.04.
Homologues: Orthologues: chimpanzee NBEAL1 (98% identical), macaque NBEAL1 (96% identical), dog NBEAL1 (92% identical), rabbit NBEAL1 (90% identical), pig NBEAL1 (90% identical), rat Nbeal1 (89% identical), mouse Nbeal1 (89% identical), guinea pig NBEAL1 (84% identical), tropical clawed frog nbeal1 (74% identical), zebrafish nbeal1 (67% identical), Caenorhabditis elegans sel-2 (16% identical), Caenorhabditis elegans wdfy-3 (16% identical). Paralogues in human: NBEAL2 (47% identical), NBEA (20% identical), WDFY3 (20% identical), LRBA (19% identical), WDFY4 (19% identical), LYST (19% identical), NSMAF (10% identical).
Diseases named in the same sentence as NBEAL1 in open-access papers:
NBEAL1 is named in the same sentence as 25 diseases in open-access papers, as found by Europe PMC text mining. Sharing a sentence is not in itself a finding about the gene and the disease. The quoted sentences say what the papers report.
Stroke (5 papers, 2020 to 2025). Sudden impairment of blood flow to a part of the brain due to occlusion or rupture of an artery to the brain. "Using PWAS, TWAS, MR and Bayesian colocalization analyses, ICA1L and NBEAL1 were proved to be causal for stroke in brains." (PMID 35449099, 2022). "SNP rs116426890 is intronic to ABI2 and is linked to the expression of CARF, ICA1L, FAM117B, and NBEAL1 which are associated with both white matter hyperintensities and fractional anisotropy, predictors of cerebral small vessel disease which is involved in strokes and vascular dementia." (PMID 36684006, 2022). "QTL variants for NBEAL1 expression in the GTEx Tibial Artery tissue colocalized with Alzheimer’s GWAS (PP4=0.81) and across all neurovascular GWASs (small vessel disease PP4=0.74, stroke and white matter hyperintensities PP4=0.84)." (PMID 41282933, 2025). "Genes ICA1L and NBEAL1 were mapped by the same locus (index SNP: rs114123510), and both are related to cholesterol metabolism, in which dysregulation promotes the pathology of atherosclerosis, MI, and strokes." (PMID 35250867, 2022). "NBEAL1 have been detected previously in a GWAS of cerebral small vessel disease and was found to affect cellular cholesterol metabolism and LDL uptake and was associated with coronary artery diseases, indicating that NBEAL1 may influence the risk of stroke by LDL." (PMID 35449099, 2022).
cerebral small vessel disease (4 papers, 2020 to 2023). Cerebral small vessel disease is the term currently used to pathological processes that affect the brain parenchymal circulation (arterioles, capillaries, and veins). "NBEAL1 was previously identified in a GWAS of migraine and cerebral small vessel disease." (PMID 36808568, 2023).
coronary artery disease (4 papers, 2020 to 2024). "A recent study has shown that NBEAL1 variants are correlated with NBEAL1 expression differences in artery tissue and an elevated risk of coronary artery disease in humans." (PMID 38882374, 2024). "Gene loci associated with coronary artery disease, including neurobeachin-like 1 (NBEAL1) and APOE, were upregulated in heart art ECs in obesity." (PMID 36400935, 2022). "Genetic variants in NBEAL1 are associated with decreased expression of NBEAL1 in arteries and increased risk of coronary artery disease in humans." (PMID 32161285, 2020).
glioma (4 papers, 2017 to 2023). A benign or malignant brain and spinal cord tumor that arises from glial cells (astrocytes, oligodendrocytes, ependymal cells). "NBEAL1 was first found higher expression in glioma tissues compared to the normal brain tissue, suggesting its correlation with the glioma." (PMID 37351287, 2023). "NBEAL1 is upregulated in gliomas and comprises the least studied of human BDCPs." (PMID 31681433, 2019). "NBEAL1 is highly expressed in glioma, with potential involvement in membrane-processing signals." (PMID 28642624, 2017).
migraine (4 papers, 2020 to 2023). "For example, the reported migraine-associated signal near calcium responsive transcription factor (CARF) displayed colocalization with neurobeachin like 1 (NBEAL1) expression in all three arterial tissues." (PMID 31917787, 2020). "However, the biological roles of NBEAL1 in the pathophysiology of migraine and headache are yet unclear and require further research." (PMID 36808568, 2023). "For example, of the five genes (CARF, ICAIL, NBEAL1, FAM117B, and WDR12) at the rs138556413 locus, ICAIL and NBEAL1 have the strongest TWAS p value with migraine as compared to other genes." (PMID 37245199, 2023). "Furthermore, nine significant tissue–gene pairs were found for migraine and UACR using GTEx tissues, including four genes (NBEAL1, FAM117B, ICA1L) mainly expressed in tissues of the nervous and cardiovascular system." (PMID 37306871, 2023).
atherosclerosis (3 papers, 2022 to 2025). A disease characterized by the build-up of fatty material and calcium deposition in the arterial wall resulting in partial or complete occlusion of the arterial lumen. "Interestingly, genetic variants of NBEAL1, a gene that is poorly understood at the functional level, also significantly increases the risk of atherosclerosis development in young individuals and promotes the risk of myocardial infarction." (PMID 36400935, 2022). "Low expression of NBEAL1 disrupts LDL levels, promoting atherosclerosis and inducing cerebral infarction." (PMID 40303468, 2025).
myocardial infarction (3 papers, 2014 to 2023). Gross necrosis of the myocardium, as a result of interruption of the blood supply to the area, as in coronary thrombosis. "Among the 60 CAD genes, the strongest association was with NBEAL1 that was also identified in gene-based analysis of whole exome sequencing for early onset myocardial infarction." (PMID 28642624, 2017). "Recently, a gene-based analyses from the NIH Exome Sequencing Project has identified the association between NBEAL1 gene and early onset myocardial infarction, emphasizing the potential contributions of genetic variation in NBEAL1 to the pathogenesis of premature atherosclerosis." (PMID 37351287, 2023).
vascular dementia (3 papers, 2022 to 2025). A degenerative vascular disorder affecting the brain. "One such example is a large deletion in NBEAL1, which colocalizes with multiple neurovascular traits, including AD and vascular dementia and is an eQTL in arterial tissue in GTEx." (PMID 41282933, 2025). "The vascular-cholesterol cluster includes NBEAL1 (Tier 1) and SCAP (Tier 3), connecting iAging5 to AD and vascular dementia through cholesterol dysregulation." (PMID 41358312, 2025).
Obesity (2 papers, 2017 to 2022). Accumulation of substantial excess body fat. "Our work identified vascular dysfunction risk genes, including Sox17, Ulk4, Nbeal1, Cdkn1a and Plec, as obesity-regulated genes in the endothelium." (PMID 36400935, 2022). "Other hypertension-associated genes impacted by obesity included Podxl and Ebf1 upregulated in lung art ECs, Nbeal1 and Tbx3 upregulated in heart art ECs and Igfbp3 with reduced expression in heart, kidney and brain art ECs." (PMID 36400935, 2022). "Both CTBP2 and NBEAL1 show altered hypothalamic expression in response to fasting and diet-induced obesity and are postulated to act upon or at synapses." (PMID 28093506, 2017).
Alzheimer disease (1 paper, 2023). A progressive, neurodegenerative disease characterized by loss of function and death of nerve cells in several areas of the brain leading to loss of cognitive function such as memory and language. "At chr2q33.2, also associated with WMH, SVS, Alzheimer’s disease and caudate volume, BG-PVS was associated with higher expression of ICA1L in brain tissues and of NBEAL1 in vascular tissues, similar to TWAS of WMH and SVS5,22." (PMID 37069360, 2023).
coronary atherosclerosis (1 paper, 2023). Atherosclerosis of the coronary vasculature. "We therefore explored the causal relationship between NBEAL1 expression in the coronary artery and coronary atherosclerosis using SMR." (PMID 37351287, 2023). "Further, the summary-data-based Mendelian randomization (SMR) analysis provided the evidence of causal relationship between NBEAL1 gene and coronary atherosclerosis, confirming the protecting effects of NBEAL1 gene and coronary atherosclerosis." (PMID 37351287, 2023). "Further, the SMR analysis provide the evidence of causal relationship between NBEAL1 gene and coronary atherosclerosis, confirming the protective effects of NBEAL1 gene and coronary atherosclerosis." (PMID 37351287, 2023). "The NBEAL1 is a new coronary atherosclerosis associated maker gene screened by four TWAS approaches in our study." (PMID 37351287, 2023). "Our results showed NBEAL1 was a plausible causal gene in the coronary artery and coronary atherosclerosis." (PMID 37351287, 2023). "Our study identified 19 novel genes by three TWAS approaches and one novel gene (NBEAL1) by four TWAS approaches associated with coronary atherosclerosis, and all these genes could be enriched in leukocyte mediated immunity reaction pathway." (PMID 37351287, 2023). "However, there is few reports on the causal relationship between NBEAL1 gene and coronary atherosclerosis." (PMID 37351287, 2023). "In depth, it is still unclear whether NBEAL1 gene associated immune inflammatory reaction could lead to the occurrence and development of coronary atherosclerosis though cholesterol metabolism pathway, and more research are needed to identify this." (PMID 37351287, 2023). "In this research, we further identified the causal relationship between NBEAL1 gene and coronary atherosclerosis though SMR analysis, and we found NBEAL1 gene was a protective causal gene maker for CAD." (PMID 37351287, 2023). "Combined with our previous enrichment analysis results, we speculate that NBEAL1 gene might mediate the development of coronary atherosclerosis through the immune inflammatory pathway." (PMID 37351287, 2023). "Once more, the single cell cluster analysis results illustrate that the NBEAL1 gene enriched in these key cells may be an important intervention target for prevention and treatment of coronary atherosclerosis." (PMID 37351287, 2023).
developmental retardation (1 paper, 2018). "One of the break points is located within the human NBEAL1-Gene locus on chromosome 2, suggesting a correlation between this gene disruption and the patient's mild developmental retardation." (PMID 29379568, 2018).
Parkinson disease (1 paper, 2025). A progressive degenerative disorder of the central nervous system characterized by loss of dopamine producing neurons in the substantia nigra and the presence of Lewy bodies in the substantia nigra and locus coeruleus. "Colocalization with Alzheimer’s and Parkinson’s disease GWAS implicated SVs at multiple loci, including TMEM106B, BIN3, and NBEAL1." (PMID 41282933, 2025).
small vessel stroke (1 paper, 2022). "In conclusion, this integrative analysis identified ICA1L and NBEAL1, whose expression and protein abundances are associated with the risk of small-vessel stroke." (PMID 35449099, 2022).
tumor (4 papers, 2014 to 2025). "Two representative overlapping genes, IFI27 and NBEAL1, were significantly associated with poor patient prognosis (IFI27, p = 0.0116; NBEAL1, p = 0.0196), suggesting their potential roles in tumor progression." (PMID 41465457, 2025). "Fifteen distinct clusters were identified and five clusters (M_C1_PLTP, M_C3_CCL20, M_C4_CXCL10, M_C5_NBEAL1, and M_C12_CD207) were abundant in tumor." (PMID 35102420, 2022).
cancer (1 paper, 2019). A tumor composed of atypical neoplastic, often pleomorphic cells that invade other tissues. "NBEAL1:p.R552* was also detected in a single female individual from CARTaGENE (of 1,919 individuals) who was cancer-free at the age of 48 years." (PMID 31681433, 2019).
NBEAL1 also shares sentences with these, for which no sentence is quoted: autism (1 paper); cerebral infarction (1); diabetes (1); Headache (1); Hereditary breast cancer (1); Hypertension (1); ischemic stroke (1); neurodegenerative disease (1); pulmonary hypertension (1).